FAM86C2P (family with sequence similarity 86 member C2, pseudogene)
Gene: Transcribed unprocessed pseudogene on chromosome 11 (67,793,196 to 67,805,313, reverse strand). Ensembl gene ENSG00000160172.
Diseases named in the same sentence as FAM86C2P in open-access papers:
FAM86C2P is named in the same sentence as 1 disease in open-access papers, as found by Europe PMC text mining. Sharing a sentence is not in itself a finding about the gene and the disease.
FAM86C2P shares sentences with these, for which no sentence is quoted: cancer (1 paper).